LAGE3 (L antigen family member 3)
Description:
Component of the EKC/KEOPS complex that is required for the formation of a threonylcarbamoyl group on adenosine at position 37 (t(6)A37) in tRNAs that read codons beginning with adenine. The complex is probably involved in the transfer of the threonylcarbamoyl moiety of threonylcarbamoyl-AMP (TC-AMP) to the N6 group of A37. LAGE3 functions as a dimerization module for the complex.
Synonyms: DXS9879E; ESO3; ITBA2; CVG5; DXS9951E; Pcc1; GAMOS2
Tractability: PROTAC: ubiquitination databases record sites on it; its protein half-life has been measured.
Gene: Protein-coding gene on chromosome X (154,477,775 to 154,479,281, reverse strand). Ensembl gene ENSG00000196976.
Subcellular location: Cytoplasm; Nucleus
Subcellular location (Human Protein Atlas): Nucleoplasm; Nuclear bodies
Pathways (Reactome):
Metabolism of RNA: tRNA modification in the nucleus and cytosol
Gene Ontology:
Molecular function: protein binding
Biological process: maintenance of translational fidelity; tRNA threonylcarbamoyladenosine metabolic process
Cellular component: cytoplasm; EKC/KEOPS complex; nuclear body; nucleoplasm; nucleus
Homologues: Orthologues: chimpanzee LAGE3 (100% identical), macaque LAGE3 (90% identical), rabbit LAGE3 (64% identical), pig LAGE3 (60% identical), dog LAGE3 (59% identical), mouse Lage3 (51% identical), tropical clawed frog lage3 (34% identical), Drosophila melanogaster Tcs6 (22% identical). Paralogues in human: CTAG1A (43% identical), CTAG1B (43% identical), CTAG2 (38% identical).
Diseases named in the same sentence as LAGE3 in open-access papers:
LAGE3 is named in the same sentence as 46 diseases in open-access papers, as found by Europe PMC text mining. Sharing a sentence is not in itself a finding about the gene and the disease. The quoted sentences say what the papers report.
Galloway-Mowat syndrome (6 papers, 2018 to 2023). Galloway syndrome is characterized by the association of nephrotic syndrome and central nervous system anomalies. "Besides, a previous study demonstrated that a recessive mutation in the LAGE3 gene encodes one of four subunits in Galloway-Mowat syndrome (GAMOS)." (PMID 33829062, 2021). "For example, mutations in OSGEP, TP53RK, TPRKB, LAGE3 and C14orf142, encoding all five subunits of the human cytoplasmic KEOPS complex, lead to defective t6A modification and Galloway-Mowat syndrome (GAMOS), characterised by early-onset nephrotic syndrome, microcephaly and brain anomalies." (PMID 32047918, 2020). "Galloway-Mowat syndrome (GAMOS) is a group of rare hereditary diseases by the combination of early onset steroid-resistant nephrotic syndrome (SRNS) and microcephaly with brain anomalies caused by WDR73, LAGE3, OSGEP, TP53RK, TPRKB, GON7, WDR4 or NUP133 mutations." (PMID 36755238, 2023). "The term “Galloway-Mowat syndrome 1 (GAMOS1)” is now used for GAMOS caused by mutations in WDR73, and “Galloway-Mowat syndrome 2-5 (GAMOS2-5)” is used for GAMOS with mutations in LAGE3, OSGEP, TP53RK, and TPRKB, respectively." (PMID 30558655, 2018). "Loss-of-function mutations in OSGEP, TP53RK, TPRKN or LAGE3, which encode the four subunits of the KEOPS complex (Kinase, Endopeptidase and Other Protein of small Size) result in Galloway-Mowat syndrome (GAMOS, #MIM251300), an early-onset nephrotic disorder with severe PM." (PMID 31832602, 2019). "We recently identified autosomal recessive mutations in genes encoding four of the five subunits of human KEOPS complex, namely LAGE3, OSGEP, TP53RK, and TPRKB in patients with Galloway-Mowat syndrome (GAMOS, OMIM#251300)." (PMID 31481669, 2019).
breast carcinoma (5 papers, 2015 to 2022). "LAGE3 expressions were confidently associated with metastatic events, tumor grades, and tumor stages in breast cancer patients with different stages." (PMID 33921749, 2021). "The results revealed that the expression of LAGE3 was elevated, compared with normal controls in breast cancer, colorectal cancer, kidney cancer, leukemia, liver cancer, lung cancer, lymphoma, melanoma, myeloma, and sarcoma respectively." (PMID 35433409, 2022). "Kaplan-Meier plots showed that overexpression of LAGE1, LAGE2A, LAGE2B, and LAGE3 were highly correlated to poor survival in most types of breast cancer." (PMID 33921749, 2021). "Secondly, the human protein atlas also revealed that LAGE3 has a higher proportion of moderate and strong intensity in breast cancer samples relative to normal breast tissues." (PMID 33921749, 2021). "Among all these, the LAGE3 gene family was particularly overexpressed in breast cancer tissues compared to normal samples in 18 analyses." (PMID 33921749, 2021). "By using a meta-analysis approach, our study suggested that, in LAGE family genes, LAGE3 has a prospective value and maybe a new biomarker and therapeutic target for future breast cancer treatment." (PMID 33921749, 2021). "Interestingly, LAGE3 showed a strong signature to be a potential biomarker for breast cancer in the results of our study." (PMID 33921749, 2021). "Moreover, through computational analysis, expression patterns of genes in cancer and normal tissues were explicitly evaluated to help us further establish the role of LAGE3 in breast cancer tissue growth." (PMID 33921749, 2021). "Since LAGE3 positively promotes the migration and invasion of HCC cells and breast cancer cells, migration and invasion of cancer cells are the key driving force for cancer metastasis and the main cause of cancer-related deaths." (PMID 35313850, 2022). "The data demonstrated that LAGE1 had weak expression and LAGE3 had the strong positive expression in breast cancer, and negative, weak expression in normal breast." (PMID 33921749, 2021). "The role of L Antigen Family Member 3 (LAGE3) in breast cancer (BC) has not been sufficiently studied." (PMID 33552947, 2020). "Indeed, the promoters of several breast cancer genes on the X chromosome, such as AR, HMGB3 and LAGE3, were hypomethylated and the mRNAs were over-expressed in MCF7 and HCC1954." (PMID 25706888, 2015). "LAGE3 expression was higher in triple-negative breast cancer (TNBC) compared to hormone receptor-positive BC, but not HER2-positive subtype." (PMID 33552947, 2020).
hepatocellular carcinoma (4 papers, 2021 to 2023). A malignant tumor that arises from hepatocytes. "LAGE3 promoted migration and invasion of hepatocellular carcinoma by facilitating the JNK and ERK signalling pathways." (PMID 37378426, 2023).
melanoma (4 papers, 2020 to 2022). A malignant, usually aggressive tumor composed of atypical, neoplastic melanocytes. "The results of qRT-PCR showed higher mRNA expression of LAGE3 in melanoma cell lines than in normal tissues." (PMID 33829062, 2021). "We explored the level of LAGE3 in normal human epidermal melanocytes (HEMa-LP) and melanoma cell lines (A375, SK-MEL-2, M21, and MEL-RM) by qRT-PCR and western blot." (PMID 33829062, 2021). "Similarly, the data demonstrated an upregulation of the LAGE3 protein in most melanoma cells compared to HEMa-LP cells." (PMID 33829062, 2021). "Our data showed an upregulation of LAGE3 in melanoma cell lines compared to normal skin cell lines." (PMID 33829062, 2021). "Moreover, we explored the level of LAGE3 in normal human epidermal melanocytes (HEMa-LP) and melanoma cell lines (SKMEL-28, LOXIMVI, and M21) by qRT-PCR." (PMID 33718105, 2020).
microcephaly (4 papers, 2020 to 2024). A congenital or acquired developmental disorder in which the circumference of the head is smaller than normal for the person's age and sex. "LAGE3 mutations are known to cause multiple human diseases, including nephrotic syndrome and microcephaly; however, its role in tumorigenesis and cancer progression is yet to be determined." (PMID 32375858, 2020).
colorectal cancer (3 papers, 2021 to 2023). A primary or metastatic malignant neoplasm that affects the colon or rectum. "Besides, the immune-related prognostic analysis of LAGE3 in colorectal cancer, clear cell renal cell cancer, and malignant pleural mesothelioma has been documented." (PMID 33829062, 2021). "Besides, it has been reported that LAGE3 was negatively correlated with the levels of infiltration for multiple immune cells, especially CD8+ T cells in colorectal cancer and clear cell renal cell carcinoma." (PMID 33829062, 2021).
liver cancer (2 papers, 2022). An epithelial or non-epithelial malignant neoplasm that arises from the liver. "The results of tissue chip staining showed that LAGE3 was highly expressed in most liver cancer tissues, but the expression rate still did not meet our expectations." (PMID 35313850, 2022).
triple-negative breast carcinoma (2 papers, 2020 to 2022). An invasive breast carcinoma which is negative for expression of estrogen receptor (ER), progesterone receptor (PR), and human epidermal growth factor receptor 2 (HER2). "In contrast, the inhibition of LAGE3 expression can restrain the proliferation, migration, and invasion of triple-negative breast cancer cell lines and induce their apoptosis in vitro." (PMID 35313850, 2022).
Alzheimer disease (1 paper, 2020). A progressive, neurodegenerative disease characterized by loss of function and death of nerve cells in several areas of the brain leading to loss of cognitive function such as memory and language. "Meanwhile, KEGG enrichment analysis demonstrated that LAGE3 was closely linked to neurodegenerative diseases (Huntington disease, Alzheimer’s disease, and Parkinson’s disease) and metabolism-related processes (Thermogenesis and oxidative phosphorylation)." (PMID 33552947, 2020).
glioblastoma (1 paper, 2023). The most malignant astrocytic tumor (WHO grade IV). "Eight genes, AC016737.2, BNC2-AS1, AC007040.1, AC009248.3, SOCAR, LAGE3, TOMM20L, and FP671120.11, were specific to patients with IDH1-wt and TERT-promoter-mutated glioblastoma." (PMID 37568598, 2023).
metastatic melanoma (1 paper, 2021). A melanoma that has spread from its primary site to another anatomic site. "Then, we used EPIC and TIMER algorithms to perform survival analysis for the high/low LAGE3-expression groups (metastatic melanoma) and high/low infiltration of CD8 T cell groups." (PMID 33829062, 2021).
non-small cell lung carcinoma (1 paper, 2021). A group of at least three distinct histological types of lung cancer, including non-small cell squamous cell carcinoma, adenocarcinoma, and large cell carcinoma. "The knockdown of LAGE3 significantly reduces cell proliferation in non-small-cell lung carcinoma cell lines." (PMID 33829062, 2021).
ovarian carcinoma (1 paper, 2020). A malignant neoplasm originating from the surface ovarian epithelium. "LAGE3 is a close analog of NY-ESO-1, probably the most immunogenic tumor antigen to date, and has been extensively explored as a target of immune recognition in several clinical trials in ovarian cancer." (PMID 32676168, 2020).
skin cutaneous melanoma (1 paper, 2021). "Here, we analyzed and profiled the LAGE3 protein in skin cutaneous melanoma (CM) using TCGA, GTEx, or GEO databases." (PMID 33829062, 2021).
cancer (11 papers, 2012 to 2024). A tumor composed of atypical neoplastic, often pleomorphic cells that invade other tissues. "Many cancer-associated and immune-related pathways of LAGE3 were enriched and identified by GO, KEGG, and GSEA." (PMID 33829062, 2021). "Stroma cells like endothelial cells and cancer-associated fibroblasts were elevated in the low LAGE3 group." (PMID 33552947, 2020). "Analysis of tumor microenvironment indicated that LAGE3 expression was associated with the immune cell infiltration and anti-cancer immunity cycle." (PMID 33552947, 2020). "We then explored the association between LAGE3 and tumor microenvironment and different steps of the cancer-immunity cycle." (PMID 33552947, 2020). "Previous studies have found that LAGE3 could be an immune-related biomarker associated with a wide variety of cancers." (PMID 35433409, 2022). "In cancer, 27% of all known human RMPs are dysregulated, among them HENMT1 and LAGE3 have been reported to be the two most frequently overexpressed genes across a wide variety of cancer types." (PMID 38198468, 2024). "Previous studies have found that LAGE3 is one of the top-ranked up-regulated RNA modification-related proteins in multiple human cancers." (PMID 35433409, 2022). "Studies have shown that LAGE3, an RNA modification-related protein, is most frequently upregulated in multiple cancer types." (PMID 35433409, 2022). "In most cancer types, LAGE3 mRNA was significantly upregulated in the cancerous tissues compared with the normal tissues." (PMID 33829062, 2021). "We revealed mRNA expression from the LAGE gene family consisting of LAGE-1, LAGE2A, LAGE2B, and LAGE-3 in 20 cancer types." (PMID 33921749, 2021). "Previous studies showed that LAGE3 was one of the most frequently upregulated RNA modification-related proteins in multiple cancer types." (PMID 33829062, 2021). "Functional enrichment analysis revealed a correlation between LAGE3 expression and biochemical metabolism and immune-related terms and cancer-related pathways." (PMID 33552947, 2020). "Previous studies reported that LAGE3 was significantly over-expressed in different types of cancer, compared to their corresponding normal tissues." (PMID 33552947, 2020). "Future work will be needed to decipher the biological role of LAGE3 and HENMT1 in cancer, as well as its potential use as a target for diagnostic and prognostic purposes." (PMID 32375858, 2020). "In addition, it was found that the down regulation of LAGE3 significantly affected the biological function of some cancer cells, including PTC and BC cell lines." (PMID 35433409, 2022). "Furthermore, we found that LAGE3 exerted cancer-promoting effects by potentiating the JNK and ERK signaling pathway." (PMID 34837962, 2021). "High LAGE3 group had higher anti-cancer immune scores in step 3 (p < 0.0001)." (PMID 33552947, 2020). "Furthermore, we identified LAGE3 mRNA expression to be positively correlated with the anti-cancer immunity cycle." (PMID 33552947, 2020). "We used TIP to visualize the activity of LAGE3 across the seven-step cancer-immunity cycle." (PMID 33552947, 2020). "In summary, the high LAGE3 group had a higher overall anti-cancer score than the low group (p < 0.001), and LAGE3 might play a positive role in the cancer-immunity cycle." (PMID 33552947, 2020). "We could observe that almost all high LAGE3 groups had higher anti-cancer immune scores in the trafficking of T cells to tumors (step 4)." (PMID 33552947, 2020). "We divided the cancer cases into high-expression and low-expression groups according to the expression levels of APC and investigated the correlation between LAGE3 expression and the prognosis of LIHC patients with the help of TCGA datasets." (PMID 35313850, 2022). "Nevertheless, our results suggest that LAGE3 and HENMT1 have altered expression levels in specific cancer types also at the protein level." (PMID 32375858, 2020).
cancer (continued). "Here, we attempted to validate the upregulation of LAGE3 and HENMT1 across a battery of 12 cancer types using tissue microarrays (TMAs)." (PMID 32375858, 2020). "Recombinant human L antigen family member 3 (LAGE3) is a part of the CTAG family ubiquitously expressed in many cell types and is often considered a notable up-regulated RNA modification-related protein in a majority of carcinoma cases." (PMID 35313850, 2022). "Moreover, we identify two enzymes, LAGE3 and HENMT1, as the top recurrently upregulated RMPs across cancer types." (PMID 32375858, 2020). "Surprisingly, we find that several commonly studied RNA modification enzymes such as METTL3 or FTO are not significantly upregulated in most cancer types, whereas several less-characterized RMPs, such as LAGE3 and HENMT1, are dysregulated in many cancers." (PMID 32375858, 2020). "Further studies need to elucidate whether LAGE3 is a crucial factor in regulating TME and the cancer-immunity cycle." (PMID 33552947, 2020). "LAGE3 appears to be ubiquitously expressed, while the two closely related LAGE1 and LAGE2 are cancer-testis antigens with high expression confined to healthy testis and cancer tissues." (PMID 22912744, 2012). "In addition, we reveal that LAGE3 regulates TME and the cancer-immunity cycle." (PMID 33552947, 2020). "However, the functions of LAGE3 in cancers have not been extensively studied." (PMID 33829062, 2021).